TIPRL (TOR signaling pathway regulator)
Diseases named in the same sentence as TIPRL in open-access papers (continued):
Sharing a sentence is not in itself a finding about the gene and the disease.
liver cancer (continued). "Furthermore, we confirmed the reproducibility of the excellent diagnostic efficacies of TIPRL, LC3 and CD133 levels in HCCs at the different IHC cohort, thus providing reliability of TIPRL, LC3 and CD133 as novel biomarkers for HCCs and early liver cancers." (PMID 31727942, 2019). "Overall, this data indicates that, as an upstream modulator of LC3 and CD133, which are involved in tumor aggressiveness, TIPRL is a critical player in HCC/liver cancer cell proliferation, viability and stemness, which are key events for HCC incidence and progression." (PMID 31727942, 2019). "Furthermore, TIPRL could best explain liver cancer patients’ survivability as a sole variable among the rest and contributes to liver cancer cell survival by stemness and self-renewal induction." (PMID 34208132, 2021). "This is supported by the observations that TIPRL knockdown inhibited survival and stemness efficacies of HCC/liver cancer cells via the reduction of autophagy, as well as the strong associations between levels of TIPRL, LC3 and CD133 in HCC and liver cancer tissues." (PMID 31727942, 2019). "Here we report the interrelationships between TIPRL, LC3 and CD133 in HCC/liver cancer tissues are associated with cancer aggressiveness via possibly induction of cancer cell stemness, thereby providing novel biomarkers for early prognosis and diagnosis of liver cancer." (PMID 31727942, 2019). "Given our previous report on the involvement of TIPRL, LC3, and CD133 in human liver cancers, we further examined the relationships between the levels in all five variables in liver disease tissues." (PMID 34208132, 2021). "In summary, the variables TIPRL, LC3, CD133, and CD44 reflect the overall survival of liver cancer patients." (PMID 34208132, 2021). "This role of TIPRL in the stemness of liver cancer cells was further supported by the observation that only TIPRL knockdown reduced the expression of LC3 and CD133 rescued by the overexpression of TIPRL." (PMID 34208132, 2021). "Recently, our team has reported that TIPRL works as a drug-resistant modulator in HCCs via suppressing the MKK7/JNK and the subsequent caspase pathways and accelerates the stemness of liver cancer cells by upregulating the expression of LC3 and CD133." (PMID 34208132, 2021). "Previously, we suggested TIPRL, LC3, and CD133 as suitable biomarker panel(s) for detecting early liver cancers." (PMID 34208132, 2021). "In keeping with this finding, TIPRL knockdown reduced survival and stemness efficacies of HCC/liver cancer cells via decreases in expressions of autophagy related- and of stemness related-genes." (PMID 31727942, 2019). "Overall, these results indicate TIPRL as a key modulator of LC3 and CD133 expressions in progress of liver cancer aggressiveness, and suggest novel links between autophagy and hepatocarcinogenesis." (PMID 31727942, 2019). "We determined significant correlations between levels of TIPRL, LC3 and CD133, as calculated by significant values of Spearman r, in each grade of liver cancers." (PMID 31727942, 2019). "In this study, we attempted to study relationships between TIPRL, LC3 and CD133, which individually has been reported in autophagy and liver aggressiveness, using human liver tissues, including HCCs, and HCC/liver cancer cell-lines." (PMID 31727942, 2019). "Either alone or as a combination, TIPRL, LC3 and CD133 showed significant values of area under the curve (AUC) and sensitivity/specificity in early liver cancer tissues." (PMID 31727942, 2019). "Here we report that the level of TIPRL is significantly correlated with levels of LC3 (Spearman r = 0.9) and CD133 (r = 0.7) in liver cancer tissues." (PMID 31727942, 2019). "Considering these criteria, we determined the strong correlation of TIPRL, LC3 and CD133 in a broad range of liver cancer tissues including HCCs." (PMID 31727942, 2019).
liver cancer (continued). "TIPRL knockdown significantly reduced expressions of LC3, CD133, stemness-related genes, as well as viability and stemness of liver cancer cell-lines, which were promoted by ectopic TIPRL expression." (PMID 31727942, 2019). "Overall, this study reports that TIPRL/LC3/CD133/CD44 could, either individually or in conjunction, serve as potential biomarkers for early liver cancer." (PMID 34208132, 2021). "TIPRL/LC3/CD133/CD44 have also provided excellent potential for prognosticating patients with grade 1 iCCA and grade 1 HCCs, together with demonstrating that TIPRL/LC3/CD133/CD44 are, either individually or in conjunction, potential biomarkers for early liver cancer." (PMID 34208132, 2021). "Given this significant correlation between levels of TIPRL, LC3 and CD133 in HCC tissues, we investigated and observed significant reductions in TIPRL, LC3, ATG7, CD133 and CD46 mRNA levels in HCC/liver cancer cell-lines transfected with two different small interfering RNA against TIPRL (siTIPRL)." (PMID 31727942, 2019). "Moreover, ectopic TIPRL promoted expressions of LC3 and CD133 as well as viability of HCC/liver cancer cell-lines, which were reduced in siTIPRL/siCD133-cells." (PMID 31727942, 2019). "Ectopic TIPRL promoted the LC3 and CD133 expressions and viability of HCC/liver cancer cells." (PMID 31727942, 2019). "Confocal observation, as well as statistical analysis consistently confirm gradual increases of TIPRL, LC3 and CD133 levels according to liver cancer progression, suggesting critical roles of TIPRL, LC3 and CD133 association in the progression of liver cancers." (PMID 31727942, 2019). "Studies have reported dysregulation of TIPRL, LC3 and CD133 in liver cancer tissues." (PMID 31727942, 2019). "In addition, we observed statistically concurrent argumentation of TIPRL, LC3 and CD133 according to the progression of liver cancers, together indicating the complex interrelationships between levels of the biomarker candidates, TIPRL, LC3 and CD133 in liver cancer aggressiveness." (PMID 31727942, 2019).
non-small cell lung carcinoma (5 papers, 2019 to 2023). A group of at least three distinct histological types of lung cancer, including non-small cell squamous cell carcinoma, adenocarcinoma, and large cell carcinoma. "In non-small cell lung cancer (NSCLC), upregulation of TIPRL enhances the autophagic activity and enables autophagy to clear metabolic and cellular stress, conferring a survival advantage to cancer cells." (PMID 37684281, 2023). "In addition, TIPRL overexpression is found to induce autophagy and accelerate growth through the eIF2α-ATF4 pathway in non-small cell lung cancer." (PMID 32719745, 2020).
gastric cancer (3 papers, 2020 to 2025). A primary or metastatic malignant neoplasm involving the stomach. "Functional study revealed that re-expression of TIPRL in gastric cancer cell lines suppressed their migratory and invasive capacities, whereas inverse effects were observed in TIPRL-deficient models." (PMID 32719745, 2020). "Clinically, loss of TIPRL expression in gastric cancer is a strong indicator of metastatic phenotype and poor clinical outcomes." (PMID 32719745, 2020). "As expected, overexpression of TIPRL induced strong phosphorylation and activation of AMPK in gastric cancer cells, whereas an inverse effect was observed in TIPRL-deficient cells." (PMID 32719745, 2020). "To substantiate the possible role of TIPRL in regulating gastric cancer tumorigenesis and progression, we adopted gain-of-function and loss-of-function assays to investigate TIPRL function in gastric cancer." (PMID 32719745, 2020). "In all, our findings strongly suggest that loss of TIPRL is associated with invasion, metastasis, and an increased risk of poor prognosis in gastric cancer." (PMID 32719745, 2020). "In keeping with our data, higher expression of TIPRL was associated with a favorable prognosis in gastric carcinoma patients according to analysis of publicly available data sets." (PMID 32719745, 2020). "Furthermore, loss of TIPRL expression serves as robust indicator for metastatic potential and unfavorable clinical outcomes in gastric cancer, where TIPRL mediates its anti-invasive effects via modulation of the AMPK/mTOR signaling axis." (PMID 40442738, 2025). "Using this high-throughput approach, we identified TIPRL (TOR signaling pathway regulator) as a novel candidate that was down-regulated in metastatic gastric cancer tissues through differential expression analysis." (PMID 32719745, 2020). "Decreased TIPRL expression was detected in clinical gastric cancer specimens, and low TIPRL expression was correlated with more-advanced TNM stage, distant metastasis, and poor clinical outcome." (PMID 32719745, 2020). "Collectively, these findings provide the first demonstration that TIPRL acts as a novel metastasis suppressor in gastric cancer." (PMID 32719745, 2020). "Herein, we identified TOR signaling pathway regulator (TIPRL) as a novel metastasis suppressor in gastric cancer through genome-wide gene expression profiling analysis using mRNA microarray." (PMID 32719745, 2020). "Taken together, the present study provides the first evidence that TIPRL, a target of miR-216a-5p/383-5p, is identified as a potential metastasis suppressor gene in gastric cancer." (PMID 32719745, 2020). "We further elucidated the molecular basis by which TIPRL exerted the suppressive effect on cell migration and invasion in gastric cancer using mRNA microarray." (PMID 32719745, 2020). "Kaplan-Meier analysis was conducted to assess the correlation of TIPRL expression with gastric cancer prognosis." (PMID 32719745, 2020). "Our clinical data urged us to investigate the putative tumor-suppressive function of TIPRL in gastric cancer in vitro." (PMID 32719745, 2020). "Consistently, our study indicated that TIPRL negatively regulated PP2A activity in gastric cancer cells." (PMID 32719745, 2020). "Therefore, in the current study, we investigated the gene expression, biological function, molecular mechanism and clinical significance of TIPRL in gastric cancer." (PMID 32719745, 2020). "However, our study indeed suggested that TIPRL functioned as a metastasis suppressor in gastric cancer through regulating AMPK/mTOR signaling." (PMID 32719745, 2020). "Furthermore, significantly shortened overall survival and disease-free survival were observed in gastric cancer patients with low TIPRL expression compared with patients with high TIPRL expression." (PMID 32719745, 2020).
gastric cancer (continued). "Here, our current study pointed out that miR-216a-5p/383-5p suppressed TIPRL expression, thus suggesting that elevation of miR-216a-5p/383-5p might contribute to aberrant down-regulation of TIPRL in gastric cancer." (PMID 32719745, 2020). "In addition, the effects of TIPRL on migration and invasion of gastric cancer cells were assessed by transwell assays." (PMID 32719745, 2020). "Our findings indicate that miR-216a-5p and miR-383-5p could directly recognize binding sites in TIPRL 3′-UTR, and TIPRL is down-regulated by miR-216a-5p and miR-383-5p in gastric cancer cells." (PMID 32719745, 2020). "Herein, we highlight a functional role for TIPRL in invasion and metastasis of gastric cancer." (PMID 32719745, 2020). "The data implied that an aberrant down-regulation of TIPRL might give rise to gastric cancer metastasis." (PMID 32719745, 2020). "Moreover, to date, no existing analyses have clarified the clinical and prognostic significance of TIPRL in human cancer, especially in gastric cancer." (PMID 32719745, 2020). "These clinical data strongly suggested that TIPRL might be involved in the metastasis and progression of gastric cancer and serve as a novel useful prognostic biomarker." (PMID 32719745, 2020). "Both assays of forced and silenced expression of TIPRL revealed that TIPRL could suppress cell migration and invasion in gastric cancer, which are two crucial events during tumor metastasis, consistent with clinical observations." (PMID 32719745, 2020). "Thus, TIPRL may represent a prognostic biomarker and a promising target for new therapies in gastric cancer." (PMID 32719745, 2020). "Therefore, the suppression of cell migration and invasion induced by TIPRL in gastric cancer might attribute, at least in part, to the TIPRL-mediated phosphorylation/activation of AMPK signaling." (PMID 32719745, 2020). "To further explore the microarray data, we evaluated the transcriptional levels of TIPRL, SERINC3, COPS6, and SELM in 40 frozen gastric tissues of gastric cancer patients by real-time PCR." (PMID 32719745, 2020). "Expression of TIPRL was also investigated by immunohistochemistry (IHC) in 104 gastric cancer samples and 86 paired non-tumor samples." (PMID 32719745, 2020). "We showed that TIPRL was frequently decreased in gastric cancer tissues, relative to non-tumor tissues." (PMID 32719745, 2020). "Taken together, TIPRL acts as a novel metastasis suppressor in gastric cancer, at least in part, through regulating AMPK/mTOR signaling, likely representing a promising target for new therapies in gastric cancer." (PMID 32719745, 2020). "Re-expression of TIPRL in MKN45 and BGC823 cells markedly suppressed the migration and invasion abilities; while the knockdown of TIPRL promoted migration and invasion of the gastric cancer cells in vitro." (PMID 32719745, 2020). "Importantly, IHC analysis of TIPRL in gastric cancer demonstrated a strong association between low expression of TIPRL and unfavorable clinicopathological variables such as more-advanced TNM stage and distant metastasis, suggesting that TIPRL down-regulation might facilitate a metastatic phenotype." (PMID 32719745, 2020). "Using microarray analysis of metastatic and non-metastatic tumors, we identified TIPRL as a novel metastasis suppressor in gastric cancer through gene expression microarray." (PMID 32719745, 2020). "Together, our findings suggest that TIPRL may induce phosphorylation/activation of AMPK, which in turn attenuates the mTOR pathway, leading to inactivation of mTOR signaling and subsequent suppression of cell migration/invasion in gastric cancer." (PMID 32719745, 2020). "We further demonstrated that TIPRL induced phosphorylation/activation of AMPK, which in turn attenuated phosphorylation of mTOR, p70S6K, and 4E-BP1, thereby leading to inactivation of mTOR signaling and subsequent suppression of cell migration/invasion in gastric cancer." (PMID 32719745, 2020).
adenosquamous carcinoma (2 papers, 2019 to 2021). A carcinoma composed of malignant glandular cells and malignant squamous cells. "In keeping with the upregulations in HCCs, TIPRL and LC3 showed significant increases in the adult hepatocytes-derived liver diseases, except for cirrhosis and adenosquamous carcinomas, compared to normal tissues." (PMID 34208132, 2021).
schizophrenia (2 papers, 2018 to 2021). A major psychotic disorder characterized by abnormalities in the perception or expression of reality. "We also examined the functional outcome of the risk allele at rs10489202 using the eQTL data of lymphoblastoid cell lines, and found that it was significantly associated with the expression of TIPRL, implicating a potential schizophrenia susceptibility gene linked to this genetic locus." (PMID 30087317, 2018). "While this preliminary attempt indicates the involvement of TIPRL in the pathogenesis of schizophrenia, the exact function of this gene and its protein product in the human brain remains poorly reported." (PMID 30087317, 2018). "The gene–disease analysis further revealed that the ATP6V1A/BNIP3 and CAMK4/TIPRL/TOMM70 signatures were associated with several brain-related disorders, including developmental disabilities, schizophrenia, intellectual disabilities, abnormal cerebral white matter morphology, and mental retardation." (PMID 34683848, 2021).
chronic hepatitis (1 paper, 2021). An active inflammatory process affecting the liver for more than six months. "We observed a significant upregulation of TIPRL, LC3, and CD44 in tissues of hepatocyte-derived liver diseases such as chronic hepatitis, hepatic steatosis, liver cell degeneration, liver tissue degeneration, and inflammation of the porta area, compared with normal tissues." (PMID 34208132, 2021).
Cirrhosis (1 paper, 2021). A chronic disorder of the liver in which liver tissue becomes scarred and is partially replaced by regenerative nodules and fibrotic tissue resulting in loss of liver function. "Contrarily, in cirrhosis, the end stage of liver fibrosis, TIPRL, LC3, and CD44 were downregulated." (PMID 34208132, 2021). "In line with the role of TIPRL in the expression of LC3, CD133, and CD44, we demonstrate the significant upregulation of TIPRL and LC3 in tissues of hepatocyte-derived liver diseases while being downregulated in cirrhosis, the terminal stage of fibrosis." (PMID 34208132, 2021).
gastric tumors (1 paper, 2020). "Similarly, assessment via IHC revealed that TIPRL protein expression was markedly down-regulated in gastric tumors compared with their normal counterparts." (PMID 32719745, 2020).
liver disease (1 paper, 2021). "Intriguingly, we observed that our training and validation sets verified the significance of TIPRL in OS of liver disease patients’ in the public DB." (PMID 34208132, 2021). "Here, we show that the variables TIPRL, LC3, CD133, and CD44 each, excluding CD46, are associated with liver disease patients’ survival." (PMID 34208132, 2021). "For the assessment, we stained tissues of human liver disease/cancer with antibodies against TIPRL/LC3/CD133/CD44/CD46, followed by confocal observation." (PMID 34208132, 2021). "Furthermore, the level of TIPRL is significantly related to liver disease and cancer patients’ overall survival." (PMID 34208132, 2021). "Furthermore, we determine that the TIPRL level was a critical play in the prognosis of liver disease/cancer patients." (PMID 34208132, 2021). "Moreover, TIPRL has a critical effect on the patient’s survival of liver diseases, including cancer, determined by our sets and public databases and KM plot analysis." (PMID 34208132, 2021). "TIPRL and LC3 were upregulated in tissues of HCCs and adult hepatocytes-derived liver diseases while downregulated in iCCA." (PMID 34208132, 2021). "Overall, our data provides evidence that the variables, TIPRL, LC3, CD133, and CD44, have a prominent effect on a prognostic role in liver disease/cancer patients." (PMID 34208132, 2021). "We observed the significant upregulation of TIPRL and LC3 in HCCs and adult hepatocyte-derived liver disease while observing downregulation in intrahepatic carcinomas (iCCA)." (PMID 34208132, 2021). "We determined a reasonable p-value in the categorical factors, subtypes, and the continuous variables, TIPRL and CD133, on the OS of liver disease patients in the validation set, even though the factors and variables in the training set have comparable values in HR and 95% CI." (PMID 34208132, 2021).